APOE (apolipoprotein E)
Diseases named in the same sentence as APOE in open-access papers (continued):
Sharing a sentence is not in itself a finding about the gene and the disease.
Anxiety (continued). "Our findings instead show the presence of higher anxiety levels in patients who are carrying APOE-ε4 and RNF219/G." (PMID 29755337, 2018). "Consistent with the mouse studies, apoE also has isoform-dependenteffects on measures of anxiety in probable AD (PRAD) patients." (PMID 17710250, 2007). "The differential effects of apoE on measures of anxiety wereassociated with neuropathological alterations in the centralnucleus of the amygdala, which plays an important role in theregulation of anxiety." (PMID 17710250, 2007). "ApoE isoforms have differential effects on measures of anxiety inApoe−/− mice expressing human apoE3 or apoE4 atsimilar levels and in PRAD subjects." (PMID 17710250, 2007). "These differentialeffects of apoE isoforms on anxiety were age-dependent and notseen in young (2–4-month-old) male mice." (PMID 17710250, 2007). "Another study focused on the anxiety-like state of apoE-TR at 12 months of age." (PMID 39833961, 2025). "A peptide, APOE-RA, which mimics the APOE function as a ligand for its receptors, alleviated both the motor learning deficit and anxiety in PAE mice, demonstrating that appropriate levels of APOE receptor-mediated signaling are essential for normal performance in various behaviors." (PMID 38734844, 2024). "Interestingly, neither treatment nor genotype affected activity in the elevated plus maze, another measure of anxiety-like behavior, so the extent to which APOE genotype more generally modulates anxiety-like and exploratory behaviors is unclear." (PMID 39629477, 2024). "On the other hand, evidence from cognitively healthy older adults suggests that APOE e4 carriage was associated with more severe self-reported depressive and anxiety symptoms irrespective of β-amyloid and more severe anxiety in β-amyloid positive individuals." (PMID 38279143, 2024). "Consistently, the percentage of time spent in open arms by PAE mice was shorter than that by control mice without treatment, but the percentage was brought back to the control level by APOE-RA treatment, suggesting that the anxiety behavior in PAE mice was also mitigated by APOE-RA treatment." (PMID 38734844, 2024). "Animal studies have suggested that the relationships between ApoE genotypes and anxiety may be mediated by changes in neurons in the amygdala." (PMID 36901420, 2023). "The results of our study showed that the level of state anxiety on the Spielberger scale was higher in carriers of the T and ε4 alleles from a population of different ages in the FKBP5 and ApoE genes, respectively, than in carriers of the T allele who lack the ε4 allele." (PMID 35205209, 2022). "Thus, ApoE−/− mice show higher anxiety values than wild-type animals by using the elevated plus maze (EPM) test." (PMID 36077225, 2022). "Anxiety symptoms are negatively associated with the right cortical surface area in APOE-4 noncarriers with SCD." (PMID 32357528, 2020). "When exploring the distribution of NPS between APOE ε4 carriers and noncarriers, only anxiety symptoms presented a significant association with this allele (p = 0.002)." (PMID 33208795, 2020). "Finally, across the whole sample and APOE ε4 carriers, we found a positive correlation between greater FC-st and higher anxiety." (PMID 32331531, 2020). "This may indicate a pleiotropic effect of the ApoE genotype on anxiety levels, as has been described with cognitive function." (PMID 32630431, 2020). "The evaluation scores of anxiety symptoms were negatively associated with the right cortical surface area in SCD APOE 4 non-carriers." (PMID 31159873, 2019). "This association which is not significant in SCD ε4 carriers verified our speculation that APOE ε4 and anxiety works on surface area distinctly and the relation between anxiety and cortical area reduction may be covered." (PMID 31159873, 2019). "Furthermore, the FC diet also reduced anxiety-related behavior in the open field in 12-month-old apolipoprotein E (apoE)-ε4/ε4 and apoE knockout mice." (PMID 24086523, 2013).
Anxiety (continued). "Remarkable changes in anxiety were found among different APOE genotypes." (PMID 22482072, 2012). "We hypothesized that human apoE isoforms have differential effectson measures of anxiety in adult (6–8 months of age)Apoe−/− mice expressing human apoE3 or apoE4 atsimilar levels." (PMID 17710250, 2007). "Inmice, apoE plays a role in the regulation of anxiety, which might involvehistamine receptor-mediated signaling and steroidogenesis in the adrenalgland." (PMID 17710250, 2007). "However, also apoE isoforms might be of importance as E2-TR and E4-TR compared to E3-TR mice show higher anxiety levels while plasma apoE levels are typically higher in E2 than E3 and E4 mice." (PMID 36720957, 2023). "Thus, although the measures of anxiety in the elevated zero maze and open field are distinct, they revealed an APP × APOE interaction at 6 and 18 months in males and females and highlight the importance of including more than one test to assess measures of anxiety." (PMID 35299942, 2022). "Although previous study showed crucial contribution of reduced neuronal activities in the anterior cingulate cortex in anxiety phenotype in the mouse with PAE, the mechanism how APOE-RA affect activities in ACC to improve the phenotype remain still elusive." (PMID 38734844, 2024). "In males, measures of anxiety in the elevated zero maze revealed an APP × APOE interaction at the 6-month time point, measures of anxiety in the open field revealed an APP × APOE interaction at the 18-month time point." (PMID 35299942, 2022). "In contrast to what was seen following an anxiety-provoking maze in our study, E2 male mice exposed to CVS showed higher levels of apoE after an acute restraint stress." (PMID 35347119, 2022). "We observed that increased state anxiety scores depend on the combination of the FKBP5 and ApoE genotypes and on the DNA methylation state of the FKBP5 promoter and ApoE genotype." (PMID 35205209, 2022). "Baseline values of anxiety (HARS-0) were significantly different between APOE-2/3 and 2/4 (p < 0.007); APOE-2/4 vs. 3/3 (p < 0.01), vs. 3/4 (p < 0.002), and vs. 4/4 (p < 0.001); and APOE-3/3 vs. 3/4 (p < 0.005) and vs. 4/4 (p < 0.02)." (PMID 33920985, 2021). "During the different phases of clinical trials, Bapineuzumab showed mild to moderate adverse events, such as headache, back pain, anxiety, and fatigue, but also more severe ones, with vasogenic edema reported in both APOE ε4 and non-APOE ε4 patients." (PMID 38791059, 2024). "The reduced activity of the cingulate cortex and anxiety behavior in mice with PAE, therefore, may depend on reduced APOE level in brain regions other than the cingulate cortex." (PMID 38734844, 2024). "Regarding the relationship between APOE e4 and anxiety, a recent study demonstrated that among patients with MCI, anxiety was less common in APOE e4 carriers compared to non-carriers." (PMID 38473892, 2024). "In particular, results showed that among APOE ε4 carriers, the proportion of anxiety was lower than among noncarriers." (PMID 33208795, 2020). "Following habituation, elevated plus-maze and open-field tasks were performed to determine whether the lack of astrocytic ApoE affected stress and anxiety." (PMID 34795427, 2021). "Therefore, our findings allow the speculation of a potential correlation between anxiety, RNF219/G, APOE-ε4 and the conversion to AD." (PMID 29755337, 2018). "As this is consistent with previous studies demonstrate higher anxiety levels in APOE4-TR and APOE-KO mice, we hypothesize that this elevated stress response may facilitate spatial learning in young E4FAD mice and mask adverse effects of apoE4 on spatial cognition." (PMID 25871877, 2015). "Although increased expression of endogenous APOE was observed in the cingulate cortex in mice with PAE by APOE-RA administration, which mitigated the anxiety behavior, no significant decrease was observed in the APOE level in the cingulate cortex in mice with PAE." (PMID 38734844, 2024).
Anxiety (continued). "Notably, anxiety scores were higher in SCD individuals and negatively correlated with surface area significantly in SCD APOE ε4 non-carriers." (PMID 31159873, 2019).
cerebrovascular disease (93 papers, 2007 to 2025). "Altogether, these results support the view that the APOE-ɛ2 allele promotes cerebrovascular disease, though the mechanisms remain poorly understood." (PMID 39229494, 2024). "The ability of APOE-ε4 to alter mTOR activity as well as autophagy flux has been suggested to increase the risk for the development of cerebrovascular disease and AD due to possible deficits in synaptic plasticity." (PMID 37238686, 2023). "Loss-of-function mutation in ABCA1 is found to be involved in familial HDL-deficiency, low ApoE plasma levels and a higher risk for AD and cerebrovascular disease." (PMID 36138870, 2022). "After adjusting for smoking, alcohol risk consumption, cardio- and cerebrovascular diseases, and APOE-ε4, the associations remained similar, except for episodic memory that became no longer associated with MetS." (PMID 34228116, 2021). "APOE‐ε4 has also been implicated in differential predilections for developing cerebrovascular disease across ethnicities (Gavett, John, Gurnani, Bussell, & Saurman, 2015)." (PMID 28948085, 2017). "The APOE ε3 allele may be associated with cerebrovascular diseases, especially in the frontal and parietal-occipital lobes." (PMID 37304017, 2023). "The APOE-e4 allele increases risk for both cerebrovascular disease and AD47,48." (PMID 38037598, 2023). "Furthermore, APOE-ε4 has been shown to affect mTOR signaling, increase mTOR activity, and alter autophagy flux that can increase the risk for the development of cerebrovascular disease and AD." (PMID 37238686, 2023). "The retinal arteriolar central reflex to vessel width ratio in digital retinal photographs was significantly higher in APOE ε4 allele carriers, hence the retina may allow for non-invasive monitoring of the effects of APOE ε4 on the cerebrovascular disease." (PMID 34831149, 2021). "Additionally, studies of the possible underlying neuropathologies of SNAP, including tangle predominant dementia, cerebrovascular disease, and argyrophilic grain disease, have highlighted an increase in disease risk among APOE ε2 allele carriers." (PMID 29190651, 2017). "Of note, APOE ε2 is not only a protective gene but might also increase the risk of certain cerebrovascular diseases and neurological disorders, which could also contribute to the reduced frequency of APOE ε2 carriers among ≥65 years old individuals in our study population." (PMID 39081475, 2022). "In addition to these four brain cell types, we also included an endothelial protein marker list derived from RNAseq data of purified brain endothelial cells to examine endothelial cell type enrichment, given the known effects of ApoE polymorphism on vascular biology and cerebrovascular disease." (PMID 30618606, 2018). "Abnormal lipid metabolism caused by genetic factors is closely related to the incidence of cardiovascular and cerebrovascular diseases, with the APOE gene being one of the most important genes affecting lipid metabolism." (PMID 36158751, 2022). "The remaining factors fell below 10% increase in error of the model if excluded: male sex (%IncMSE = 9.24), APOE ε4 carriership (%IncMSE = 8.45), brain weight (%IncMSE = 8.50), Thal amyloid phase (%IncMSE = 4.17), and Kalaria cerebrovascular disease scale (%IncMSE = 3.61)." (PMID 38619853, 2024). "APOE-ε4 during SARS-CoV-2 infection and long COVID may result in cognitive loss and cerebrovascular disease in the nervous system." (PMID 37238686, 2023).
cerebrovascular disease (continued). "The other potential factors such as sleeping disturbance, ApoE type, physical activity, and cerebrovascular disease are ideally also to be analyzed, because they may be linked to disease progression through amyloid and tau deposition or other pathways." (PMID 36034127, 2022). "Moreover, just as the apolipoprotein E (ApoE) gene contributes to the disease progression of AD, ApoE is also a genetic risk factor for sporadic CAA and cerebrovascular disease." (PMID 32183293, 2020). "Aside from small sample sizes and different analytic methods, differences in findings of age-related CBF change might also be attributable to vascular risk factors, sub-clinical cerebrovascular disease, sedentary behavior, APOE genotype, and AD family history." (PMID 30065646, 2018). "Our data also raise the possibility that African American race may modify the relationship between an MRI marker of cerebrovascular disease and cognition, likely through an APOE-independent mechanism." (PMID 29096697, 2017). "Nevertheless, it has been also shown that, unlike ε2/ε3, the ε2/ε2 APOE genotype was linked to higher levels of serum triglycerides which may exacerbate cerebrovascular disease, when compared with ε3/ε3." (PMID 34193248, 2021). "However, APOE*ε2 is not entirely benign; APOE*ε2 carriers exhibit increased risk of certain cerebrovascular diseases and neurological disorders." (PMID 33148290, 2020). "As highlighted in the introduction, the APOE ε2 allele is particularly interesting to evaluate in the context of SNAP because it has a well-documented protective effect on AD pathology, yet it has been associated with an increased risk of cerebrovascular disease." (PMID 29190651, 2017). "Besides, two studies demonstrated that APOE-ε4 carriers have higher WMH than APOE-ε4 non-carriers, whereas other studies found that APOE-ε4 allele might be independent of cerebrovascular disease." (PMID 35351867, 2022). "We found that genes related to cerebrovascular diseases, such as COL4A1, COL4A2, VCAN and APOE were significantly enriched in the cerebrovascular ECM network." (PMID 33730931, 2021). "From our point of view, the effect of APOE genotype on TDP-43 accumulation in patients with AD should be carefully interpreted, since APOE affects core AD neuropathology and cerebrovascular disease, both of which also interact with TDP-43." (PMID 32581773, 2020). "Risk assessment will encompass the twelve modifiable risk factors identified by The Lancet Commission in 2020, apolipoprotein E (APOE) genotyping, and assessment of biological indicators of brain disease such as brain beta-amyloid, brain tauopathy, neurodegeneration, and cerebrovascular disease." (PMID 40102145, 2025). "A recent mechanistic study on APOE4-related cerebrovascular disorders did not include APOE ε2 (APOE2) -containing genotypes, and the role of APOE2 as a protective versus predisposing factor is under debate and seems to vary according to condition." (PMID 34949230, 2021). "Baseline differences in cerebrovascular disease between ApoE ε4 carriers and non-carriers in our cohort may partially explain differences in glucose hypometabolism." (PMID 30991617, 2019). "As a limitation to our study, it should be noted that other pathologies, such as intraneuronal protein deposits and cerebrovascular disease, may explain differences in glucose hypometabolism between ApoE ε4 carriers and non-carriers in our study." (PMID 30991617, 2019). "Thus, in a population with low levels of cerebrovascular disease and a lower prevalence of SNAP than the general population, APOE and known genetic drivers of AD do not appear to contribute to the neurodegeneration observed in SNAP." (PMID 29190651, 2017).
vascular dementia (92 papers, 2010 to 2026). A degenerative vascular disorder affecting the brain. "We also found the known rs429358 variant of APOE associated with AD, PD, vascular dementia (VD), primary progressive aphasia (PPA), and dementia with Lewy Bodies (DLB)." (PMID 38693203, 2024). "For example, a meta-analysis showed that APOE ε4 was strongly associated with susceptibility to vascular dementia in Chinese population." (PMID 39639910, 2024). "All patients with vascular dementia were APOE ε3 carriers (7 patients homozygous for the ε3 allele and 4 patients being heterozygous for the ε3 allele)." (PMID 35912087, 2022). "Significant positive association has been found in APOE ε4 carriers,increasing the risk of developing vascular dementia as compared to ε2 and ε3carriers." (PMID 33907599, 2021). "The strongest genetic risk factor for AD is the ε4 variant of apolipoprotein E (ApoE), yet the most common cause of vascular dementia (VaD) is cerebral small vessel disease." (PMID 32545722, 2020). "For example, the ε4 allele of apolipoprotein E (APOEε4), the greatest risk factor for late-onset AD and Vascular Dementia, is associated with early cerebrovascular decline in both mice and humans." (PMID 31726991, 2019). "For future studies, we intend to investigate the influence of APOE genotype on the plasma lipidome, as well as identify lipidomic changes associated with vascular dementia." (PMID 31496985, 2019). "Evidence from a meta-analysis of 29 studies suggested that APOE gene polymorphisms was associated with the risk of vascular dementia." (PMID 26830841, 2016). "A meta-analysis of 29 studies included 1,763 cases and 4,534 controls provided evidence for an association between APOE gene polymorphisms and the risk of vascular dementia." (PMID 24456740, 2014). "The ε4 variant of the APOE gene seems to be a major risk factor for both degenerative and vascular dementia." (PMID 22482072, 2012). "This exclusion could lead to selection bias, which could overestimate the association between APOE and AD pathology by reducing the representation of individuals with mixed or predominantly vascular dementia." (PMID 41268805, 2025). "In addition, a synergism has been observed between SNPs PON1 Q192R and L55M and apolipoprotein-E (Apo-E) for susceptibility to AD, as well as vascular dementia (VD)." (PMID 33374313, 2020). "Age-related diseases such as Alzheimers, and vascular dementia and cardiovascular risk have been regularly associated with the ApoE gene and particularly the ApoE4 allele which tracks with higher lipoprotein values." (PMID 25773008, 2015). "Protein-protein interaction (PPI) network analysis revealed that APOE acts as a major hub connecting several key pathways involved in vascular dementia (VaD)." (PMID 41032496, 2025). "By analyzing the keywords used in research articles, it has been noted that early studies primarily concentrated on vascular dementia, population, clinical determinants, base line frequency, apolipoprotein E, and informant questionnaire." (PMID 39440254, 2024). "There is a clear accumulation of APOE-4 carriers among patients with AD (APOE-3/4 30.30%; APOE-4/4 6.06%) (P < 0.001) and vascular dementia (APOE-3/4 35.85%, APOE-4/4 6.57%) (P < 0.001) as compared to controls." (PMID 22482072, 2012). "In a Korean study, a comparison between patients with AD, vascular dementia (VD), and normal controls suggest that ApoE ε4 allele was not more prevalent in the VD patients." (PMID 40349252, 2025). "The study found that regular use of glucosamine supplements was substantially linked to a reduced risk of developing vascular dementia in older individuals, regardless of their APOE genotypes and baseline cognitive ability." (PMID 39764251, 2024). "Regardless of APOE genotypes and baseline cognitive function, habitual glucosamine use was significantly inversely associated with incident vascular dementia in the older population." (PMID 37689747, 2023).